DNMT3A (DNA methyltransferase 3 alpha)
Diseases named in the same sentence as DNMT3A in open-access papers (continued):
Sharing a sentence is not in itself a finding about the gene and the disease.
tumor (continued). "The tumor suppressor effect of DNMT3A was demonstrated in a mouse squamous-cell carcinoma model, which became even more aggressive in the concomitant absence of Dnmt3b." (PMID 39819598, 2025). "DNMT3A have similar effects as a tumor suppressor in hematopoietic cells; therefore, in 20–30% of various hematologic disorders Dnmt3a mutations seems to have a causal role in their development." (PMID 39819598, 2025). "In order to validate this finding, we analysed the expression of the DNMT3a protein and the clinical significance of DNMT3a by IHC staining in a paraffin-embedded tissue microarray containing 119 paired tumour and normal tissue samples." (PMID 39990668, 2025). "WES of purified, neoplastic T‐cell (CD3+PD1+) demonstrated high concordance with whole tumor biopsies and validated the presence of TET2 and DNMT3A in tumor and non‐lymphoid cells, but other mutations (CD28, RHOAG17V, IDH2R172, PLCG1) in neoplastic cells." (PMID 40510016, 2025). "The impact of the tumor environment was evaluated in the same patient population against the expression of DNMT3A and GMPS." (PMID 41465346, 2025). "One plausible explanation is that mutations in epigenetic modifiers (e.g. DNMT3A) are likely initiating events, whereas those in signaling genes (e.g. FLT3) drive rapid tumor growth, resulting in diagnosis with fewer subsequent mutations." (PMID 40662787, 2025). "Mutations in DNMT3A and TET2 were detected in the majority of patients with AITL in both pre-treatment tumours (8/12 and 11/12, respectively) and in ctDNA where available (5/6 and 6/6, respectively)." (PMID 40724970, 2025). "CREBBP, CEBPA, and DNMT3A are tumor suppressor genes whose dysfunction has been reported in hematologic malignancies." (PMID 40216811, 2025). "DNMT3A has been identified to be an ideal target for the development of personalized treatment or prediction of tumor prognosis." (PMID 41450820, 2025). "Within our BCAC cohort, we identified 1 significantly recurrent focal deletion encompassing a 18 Mb region on chromosome 2 that included the tumour suppressor genes DNMT3A and ASXL2." (PMID 40389436, 2025). "The siRNA specifically targets the DNMT3A mutation and FLT3ITD mutation in AML, leading to reduced clonal growth of AML cell lines in vitro and inhibiting tumor growth in xenograft cell lines in vivo." (PMID 39078434, 2025). "We previously used conditional knockout mice to elucidate a tumor suppressor function for Dnmt3a in T-cell transformation." (PMID 40552132, 2024). "We previously used a conditional knockout mouse model to uncover a tumor suppressor function for Dnmt3a in T-cell transformation." (PMID 40552132, 2024). "Prior research into NR6A1/DNMT3A signaling in relation to tumor cell resistance remains limited, with only a few studies addressing this association." (PMID 39624078, 2024). "For DNMT3A, although IHC data exhibited intrapatient heterogeneity in some tumors with different intensities in different tumor areas, a general trend of high CD8 + TILs associated with weak staining of DNMT3A was observed and vice versa." (PMID 37847338, 2024). "To determine the role of DNMT3A in GBC metastasis, we evaluated the expression of DNMT3A in fresh frozen tumor tissues derived from patients with GBC." (PMID 38380551, 2024). "Additional research is needed to estimate the frequency of NR6A1/DNMT3A inhibition among resistant cancer cells and to delineate the perspective of using the current parameters as an adjunctive prognostic criterion for tumor resistance." (PMID 39624078, 2024). "Similar to DNMT3A R882H mutation, DDX43 has been shown to be involved in tumor cell development in many types of cancers." (PMID 38807916, 2024). "To identify the correlation between DNMT3A and YAP, we performed tumor metastasis‐associated gene expression profiling in DNMT3A‐depleted and control GBC cells using a PCR array." (PMID 38380551, 2024).
tumor (continued). "The study elucidated that EGCG attenuates DNMT activity and protein levels, encompassing DNMT1, DNMT3a, and DNMT3b, reinstates tumor suppressor genes, and diminishes cell proliferation, thereby offering a multifaceted approach to cancer treatment." (PMID 38879474, 2024). "F. nucleatum was confirmed to cause promoter hypermethylation of tumour suppressor genes by increasing the expression of DNMT1 and DNMT3A (DNA methyltransferase) in vitro and in vivo." (PMID 38536233, 2024). "It was also recently noted that deletion of DNMT3A in T-cells can prevent T-cell exhaustion and enhance anti-tumor activity." (PMID 39456832, 2024). "Our results showed that NSUN2, DNMT1, DNMT3A, DNMT3B, TRDMT, and ALYREF were related to high or low tumor risk, while NOP2 was related to the pTNM stage of tumors." (PMID 38579085, 2024). "In fact, inactivation of TET2 and deletion of DNMT3A have proven to be efficient in potentiating anti-tumor immunity by adoptively transferred cells." (PMID 38321550, 2024). "The present study showed a higher protein expression of DNMT3A in tumor samples than in surrounding healthy tissue samples." (PMID 38246976, 2024). "DNMT3A-mediated hypermethylation led to the reduction of tumor suppressor genes, thereby contributing to the development of cancers." (PMID 37085288, 2023). "CRISPR-Cas9 can be used to generate CAR-T cells with DNMT3A knocked out with consequent constant proliferation and successful control of tumor development in vivo, exhibiting the benefits of targeting DNMT3A in immunotherapies." (PMID 37064017, 2023). "Consistent with the role of miR-29s in cancer, their targets DNMT3A and DNMT3B have been described as overexpressed in various neoplasms and associated with poor prognosis in numerous tumors, including BC." (PMID 37373065, 2023). "Recently, deletion of DNA methyltransferase 3A (DNMT3A) was shown to preserve the antitumor activity of CAR-T cells during prolonged tumor exposure." (PMID 37880715, 2023). "DNA methylation induced by DNMT3A has been shown to play a key role in chromatin accessibility and T-cell exhaustion, and the tumor killing effect of chimeric antigen receptor T-cell immunotherapy (CAR-T) after DNMT3A knockout is significantly enhanced." (PMID 37355637, 2023). "Next, we determined the effect of EGCG on DNA methylation and DNMT1, DNMT3a, and DNMT3b expression in tumor tissues." (PMID 36979768, 2023). "DNMT3A knockdown decreased tumor weight and volume, which was consistent with the findings from in vitro experiments." (PMID 37085288, 2023). "In each patient, and in agreement with the original report, we discovered a cluster(s) corresponding to the neoplasm along with the corresponding driving mutations in JAK2, DNMT3A and TET2 genes." (PMID 37026484, 2023). "Consistent with the in vitro findings, HGFAC protein levels increased significantly, and DNMT3A levels were decreased in tumor tissues from nude mice with increased miR-4270 expression." (PMID 38077422, 2023). "It is now known that AITL, CMML and AITL-derived DLBCL are neoplasms that share common age-related ancestral mutations (TET-2 and DNMT3A)." (PMID 37182145, 2023). "In murine breast cancer and glioma models, DNMT3A knockout CAR-T cells significantly suppressed tumor growth and prolonged survival." (PMID 37398660, 2023). "In conclusion, our study revealed that DPT is under-expressed in BC, which results from DNMT3a-mediated aberrant hypermethylation of its promoter, and functions as a tumor suppressor." (PMID 36774339, 2023). "The tumor demonstrated monoclonal TR gene rearrangement and mutations of TET2 and DNMT3A, which are uncommon in ENKTL." (PMID 37646869, 2023). "Epigenetically altered CAR-T cells with modulated DNMT3A have been studied to further understand the role of DNMT3A in anti-tumor activities." (PMID 37064017, 2023). "The miR-29 family was reported to function as tumor suppressor microRNA through sponging DNMT3A and DNMT3B." (PMID 36870998, 2023).
tumor (continued). "CAR-T cells depleted of DNMT3A were able to control a tumor rechallenge 148 days after the initial tumor challenge, which is indicative of long-term memory." (PMID 37880715, 2023). "Knockdown of DNMT3A or overexpression of miR-532-3p suppressed PC cell proliferation, invasion, and migration, as well as tumor formation in nude mice." (PMID 37085288, 2023). "Another crucial reprogramming method for increasing anti-tumor efficacy is via DNA methyltransferase 3A (DNMT3A), an enzyme that catalyzes 5-methylcytosine methylation." (PMID 37064017, 2023). "As a family member of DNA methyltransferases, DNMT3A can catalyze de novo DNA methylation in CpG islands of gene promoters, resulting in the silencing of the tumor suppressor genes in multiple cancers." (PMID 36291095, 2022). "Once MDM2 is overexpressed, RB expression drops and RB-mediated suppression of DNMT3A activity is diminished, which results in overactive DNMT3A catalyzing DNA methylation and silencing of tumor suppressor genes." (PMID 36296971, 2022). "The genes most commonly mutated in clonal hematopoiesis are the epigenetic regulators DNMT3A and TET2, and other commonly mutated genes include regulators of HSC proliferation and tumor suppression." (PMID 36097025, 2022). "It was indicated that miR-34a-5p/c-MYC/DNMT3a axis regulated PTEN to suppress CRC tumor growth in vivo." (PMID 34623601, 2022). "It has also been found that the SALL3 gene, is upregulated by stilbenes, which down-regulates DNMT3A (DNA (cytosine-5)-methyltransferase 3A), binding to the promoters of tumour suppressor genes such as SEMA3A." (PMID 36557789, 2022). "In this study, we conducted Sanger sequencing of formalin-fixed paraffin-embedded (FFPE) diagnostic tumor samples using a target-panel to search for recurrent mutations involving the IDH-1/IDH-2, TET-2, DNMT3A and RhoA genes in 59 cases of nMTCL." (PMID 36536430, 2022). "The panel-targeted sequencing results of tumor specimens revealed high incidences of oncogenic PIK3CA and DNMT3A mutations in patients aged ≥65 years, which highlighted the impact of age-dependent genomic alterations on CRC tumorigenesis." (PMID 35203549, 2022). "In the present study, miR-26a-5p exerted tumor suppressor in NSCLC by targeting DNMT3A and then suppressing cancer stem cell-like properties in NSCLC by inactive Wnt/β-catenin signaling pathway." (PMID 35860691, 2022). "Genomic profiling of AITL, DLBCL, and MDS samples revealed that the tumor cells from all samples shared common mutations in TET2 and DNMT3A." (PMID 35846192, 2022). "Of interest, MDM2 is implicated in promotion of cell cycle progression and inhibition of apoptosis, as well as in the epigenetic silencing of tumor suppressor genes through RB/DNMT3A-dependent pathway." (PMID 36296971, 2022). "Normally, DNMT3A-mediated hypermethylation of promoter on tumor suppressor genes or oncogenes restrains gene expression, which regulate tumor initiation, metastasis, and progression." (PMID 35860691, 2022). "The mutational landscape of AITL/TCL‐TFH has been well characterized, with frequent early occurrence of TET2 and DNMT3A mutations in haematopoietic stem cells, and RHOA‐G17 and IDH2‐R172 mutations as later pathogenic events in tumour cells only." (PMID 35064935, 2022). "According to genomic datasets derived from 123 CRC tumor specimens in this study, the number of PIK3CA and DNMT3A mutations was significantly increased in patients aged over 65 years (p = 0.032 and 0.039, respectively)." (PMID 35203549, 2022).
tumor (continued). "On the other hand, there are hints in literature of seemingly paradox functions of DNMT3A as a potential tumor suppressor, for instance in lung tumors, the physiological relevance of this is still a matter of debate." (PMID 36457063, 2022). "The tumor cells of AITL, DLBCL, and MDS in this patient shared common mutations in TET2 and DNMT3A, suggesting that hematologic malignancies in the three lineages evolved from a common founder clone." (PMID 35846192, 2022). "To date, several tumor cell biomarkers, including MDM2/4, epidermal growth factor receptor mutation, DNMT3A, and FGF3/4/19, have been shown to be associated with HPD." (PMID 36428951, 2022). "siRNAs directed specifically against two common mutated genes in the AML, the DNA-methyltransferase DNMT3A and FLT3-ITD lead to a reduction of clonal growth in vitro in AML cell lines and inhibit tumor growth in vivo in xenotransplanted cell lines." (PMID 36457063, 2022). "NSUN2, NSUN5, NSUN6, DNMT3A, DNMT3B, ALYREF, and TET3 acted as tumor risk factors, and overexpression of these genes led to a poorer prognosis for ccRCC patients." (PMID 36661693, 2022). "Taken together, we indicated that miR-26a-5p played as a tumor suppressor, and DNMT3A acted as an oncogene to repress SFRP1 expression by enhancing DNA methylation." (PMID 35860691, 2022). "Nonetheless, DNMT3A has some properties that indicate it is also a tumor suppressor in hematologic malignancies." (PMID 36091786, 2022). "Our results revealed that miR-26a-5p acted as a tumor suppressor through targeting DNMT3A to upregulate SFRP1 via reducing DNMT3A-dependent DNA methylation." (PMID 35860691, 2022). "The paradoxical effect promoted more researchers to focus on the exploration of DNMT3A, which is conducive to further leaps in tumor-targeted therapy." (PMID 36091786, 2022). "A recent study showed that SYC-52221 and EPZ004777 inhibitors that target DOT1L, decrease tumor cell proliferation and induce cell apoptosis, cycle arrest, and terminal differentiation in DNMT3A mutant cell lines in a dose- and time-dependent manner." (PMID 36338673, 2022). "DNMT3A is a de-novo methyltransferase, which is considered to bring about silencing of some critical genes during tumorigenesis, including tumor suppressor genes, and genes involved in cell cycle regulation, transcription regulation, and signal transduction." (PMID 34298793, 2021). "In fact, the contradictory roles of the TET enzyme as a tumor suppressor and as an oncogene have also been observed in other epigenetic regulators such as DNMT3A and EZH2." (PMID 34209564, 2021). "They reported a significant increase in DNMT3A expression in poorly differentiated tumours compared to well-differentiated tumours (p > 0.01)." (PMID 34439335, 2021). "DNMT3A belongs to a family of de novo DNA methyltransferases and has traditionally been considered an oncogene, but can also act as a tumor suppressor under certain circumstances." (PMID 34944992, 2021). "Specifically, DDX3 reduction can inhibit tumor-suppressive miRNA expression, promote up-regulation of DNA methyltransferase 3A (DNMT3A), enrich DNMT3A binding on promoters of tumor-suppressive miRNAs, and cause hypermethylation." (PMID 34368140, 2021). "Tissue microarray contains GBC tumour tissues was used to evaluate the association between the expression of ELP5, DNMT3A and PAX5." (PMID 34823564, 2021). "Inhibition of DOT1L by EPZ5676 suppressed tumor growth, reduced colony-forming capacity, and induced terminal differentiation in DNMT3A-mutant AML cells." (PMID 34012921, 2021). "In HBV-HCC pathogenesis, a direct epigenetic target of this miRNA is DNMT3A which targets a range of tumor suppressors." (PMID 33995383, 2021).
tumor (continued). "In several malignancies, DNMT3A has been shown to influence cellular apoptosis, cisplatin resistance, tumor growth, and metastasis." (PMID 34872548, 2021). "The expression level of TYMS was negatively correlated with microsatellite instability (MSI) and Tumor mutation burden (TMB), and positively correlated with methylase expression in DNMT1, DNMT2, DNMT3A and DNMT3B." (PMID 35003215, 2021). "In tumor case 41, BRAF p.V600E and DNMT3A p.P904L mutations were both present at clonal allele frequencies of 32%, indicating their acquisition early during tumorigenesis and presence in the majority of tumor cells." (PMID 34661724, 2021). "They then exposed the mice to the chemical carcinogen, DMBA/TPA, and found that mice lacking Dnmt3a, but not Dnmt3b, displayed epidermal squamous malignancies earlier than wild type mice, suggesting that Dnmt3a plays a tumor suppressive role in the epidermis." (PMID 34298617, 2021). "Notch1 and DNMT3A are not only related to the proliferation of tumor cells, but also to the regulation of invasion and metastasis, which can influence patient prognosis." (PMID 35087829, 2021). "A concurrent 825 tumor-related gene panel for thoracolumbar metastases revealed several other likely pathogenic variants (ANTXR1 and below), among which DNMT3A is predicted to be an epigenetic driver of high malignancy and dismal prognosis." (PMID 34796114, 2021). "During EMT, HMGA2 promotes the binding of the de novo DNA methyltransferase 3A (DNMT3A) to the Cdh1 promoter, inducing the hypermethylation and silencing of the tumor-suppressor E-Cadherin (CDH1); this causes tumor cell invasion." (PMID 34439740, 2021). "Recently, miR-29b-3p was proven as the tumor promoting factor of bladder cancer via suppressing DNA methyltransferase 3A (DNMT3A)." (PMID 34148029, 2021). "DNMT3A is a member of the DNA methyltransferase (DNMTs) family, and is known as a crucial factor in the tumor epigenetic mechanism that functions in de novo methylation." (PMID 34148029, 2021). "In liver cancer, DDX3X affects the levels of a subset of tumour-suppressive miRNAs by reducing DNMT3A (DNA methyltransferase 3A) binding and hypermethylation on the promoter regions of these miRNAs." (PMID 33627125, 2021). "Consistent with their roles in DNA methylation and with the direction of associations in the pancancer dataset, DNTM1, DNMT3A, and DNTM3B expression was associated with increased methylation of many individual probes and gene regions in multiple tumor types." (PMID 33676569, 2021). "Ectopic expression of miR-143 inhibits cell growth, reduces clone formation; restored miR-143 expression decreases tumor cell growth and soft-agar colony formation, and downregulates DNMT3A expression." (PMID 32906681, 2020). "ChIP analysis revealed that SUV39H1 regulated the expression of DNMT3A by improving H3K9me3 level acting on the − 1000 to + 1 region of the promoter region of DNMT3A in tumor tissues." (PMID 32699524, 2020). "In nude mice xenografts, the IHC results showed that DNMT3A was less expressed in RP11‐159K7.2 knockout tumour tissue than those in control." (PMID 32363688, 2020). "The paradoxical effect of DNMT3A led us to ask the following questions: How do the alterations in DNMTs affect the tumor?" (PMID 32751889, 2020). "With regard to tumor suppressors, DSV–iECs showed an equal divide: 2 up-regulated (mutations: DNMT3A; CNAs: FANCA) and 2 down-regulated (CNAs: IRF1, BTG1) genes." (PMID 32934781, 2020). "DNMT3a has recently emerged as one of the most important tumor suppressors in hematological malignancies, in particular in AML cells, featuring a high number of mutations that are involved in resistance to some types of drugs." (PMID 32225105, 2020). "Wildtype DNMT3a has a tumor-suppressing role through preventing HIF2α-dependent hypoxic cancer cell proliferation." (PMID 33088284, 2020).